TIMP2 (TIMP metallopeptidase inhibitor 2)
Diseases named in the same sentence as TIMP2 in open-access papers (continued):
Sharing a sentence is not in itself a finding about the gene and the disease.
cancer (continued). "We next measured the effect of PA on mRNA and protein expression of MMP-2, MMP-9, TIMP-1, and TIMP-2 (which have critical roles in cancer cell migration and invasion) in HeLa cells by use of western blotting and RT-qPCR." (PMID 29267213, 2017). "Due to its dual roles, TIMP-2 has been reported to have both pro-tumorigenic and anti-tumorigenic roles in cancer." (PMID 26361584, 2015). "Simultaneous increase of MMP2 and decrease of TIMP2 levels were observed in malignant tumors compared to benign tumors and the normal ovary, with this imbalance indicative of the importance of MMP2–TIMP2 levels in promoting invasion." (PMID 26579497, 2015). "In the present paper, the tissue expression of MMP-2 and TIMP-2 was observed in cancer and interstitial inflammatory infiltrate cells as well as in normal colorectal epithelium." (PMID 24395652, 2014). "This same study found that forced TIMP-2 expression in A549 cells significantly reduced recruited MDSCs, which are believed to induce angiogenesis and cancer immunosuppression, in tumors and suppressed angiogenesis and tumor growth." (PMID 26056585, 2014). "Taken together, these studies suggest that TIMP-2 promotes an anti-tumor transcriptional profile in cancer cells." (PMID 26056585, 2014). "The expression of TIMP-2 in inflammatory cells correlated significantly with the expression of this protein in cancer and normal cells (p < 0.001 and p = 0.004, respectively)." (PMID 24395652, 2014). "MMP-9 and TIMP-2 can affect the progression of cancer, which is valuable for studies on oral and maxillofacial SCC genes." (PMID 24829764, 2014). "The serum levels of MMP-2 and TIMP-2 in cancer patients were significantly lower than those in control group, but the percentage of positive immunoreactivity of these proteins were higher in malignant and inflammatory cells as compared to normal tissue." (PMID 24395652, 2014). "Serum levels of MMP-2 were significantly higher in patients with positive expression of this protein in cancer cells (p = 0.047) as well as in patients with positive expression of TIMP-2 in inflammatory (p < 0.001) and normal colorectal cells (p = 0.04)." (PMID 24395652, 2014). "A further understanding of the underlying molecular mechanisms and signaling pathways involving TIMP-2 and the regulation of tumor growth and progression will allow for its full exploitation as a candidate for cancer therapy." (PMID 26056585, 2014). "TIMP2 possesses a complex role in cancer through its ability to regulate MMP activity and to inhibit especially MMP2." (PMID 25136829, 2014). "TET1 partly suppresses invasion in cancer by binding to TIMP2/3 and demethylating the promoters to activate TIMP2/3, and in turn down-regulates MMP expression." (PMID 24363660, 2013). "In 1 month following the operation, the highest level of MMP-2 was also in patients with unresectable cancer and the highest level of TIMP-2 in patients with inflammatory tumors." (PMID 23768069, 2013). "Significantly increased mRNA expression of MMP-2 and MMP-9 and decreased expression of TIMP-1 and TIMP-2 was observed in the cancer-induced group." (PMID 23599733, 2013). "Furthermore, an increase in serum adiponectin might reflect favourable effects of radioiodine administration on cardiovascular and cancer risk factors, while an increase in TIMP-2 (principal MMP-2 inhibitor) might lead to a decrease in free MMP-2 concentrations." (PMID 23107223, 2012). "Reverse zymography revealed up regulation of TIMP-2 activity with NM treatment in all cancer cell lines in a dose-dependent manner." (PMID 22736175, 2012). "However, virus-mediated TIMP-2 gene therapy in humans may limit its therapeutic application due to safety concerns, including cytotoxicity and immune responses, along with it being a possible causative agent of cancer." (PMID 22545131, 2012). "In our experiment, PE downregulated the expression of MMP-2 and MMP-9, and activated TIMP-2, revealing a double strength anti-cancer effect." (PMID 21799674, 2011).
cancer (continued). "The mean levels of serum TIMP-2 and MMP-2-TIMP-2 complex were higher in the healthy controls compared to those with a malignant tumor." (PMID 20671952, 2010). "We focus on the roles of MMP and TIMP-2 in modulating inflammation and cancer progression in solid tumors." (PMID 21152266, 2010). "MMP-2 and MMP-14 mRNA was detected primarily in reactive stromal cells whereas TIMP-2 mRNA was expressed by both stromal and cancer cells." (PMID 16776850, 2006). "There remains considerable debate regarding the role of TIMP2 in cancer." (PMID 41463322, 2025). "In addition, patients with TIMP-2-negative carcinomas experienced significantly shorter disease-free survival compared to those with TIMP-2-positive tumors." (PMID 38673838, 2024). "Moreover, miR-106a overexpression in PC is correlated with pancreatic tumorigenesis by inducing cancer cell proliferation, epithelial–mesenchymal transition, and invasion by targeting tissue inhibitor of metalloproteinase-2 (TIMP-2)." (PMID 37627777, 2023). "TIMP-2 is downregulated or silenced in a variety of cancers." (PMID 38276258, 2023). "In addition, new research indicates that miR-106a has an oncogenic function in the development of pancreatic tumors by facilitating the proliferation, EMT, and invasion of cancer cells by focusing on tissue inhibitors of metalloproteinase 2 (TIMP-2)." (PMID 37986065, 2023). "Likewise, MMP2, MMP9, MMP14, and TIMP metallopeptidase inhibitor 2 (TIMP2) have also shown similar results, thus indicating the relevance of matrix remodelers in cancer invasion." (PMID 38009093, 2023). "Comprehensive understanding of the TIMP2 may have guiding significance for the prognostic judgments, early diagnosis, and targeted therapy of in cancer patients." (PMID 36304987, 2022). "TIMP2 has been explored at the single-cell resolution in sixteen types of cancers." (PMID 36304987, 2022). "TIMP2 is therefore an important target in the management of cancer metastasis." (PMID 36291151, 2022). "Consistent with theoretical expectations, as an MMP inhibitor, TIMP2 was downregulated in many cancer types, and its high expression may indicate a better prognosis." (PMID 35300408, 2022). "Furthermore, CYP4Z1 overexpression promoted the expression of the vascular endothelial growth factor A (VEGF-A) and decreased the expression of the tissue inhibitor of metalloproteinases 2 (TIMP-2) in cancer cells compared to control cells." (PMID 36143940, 2022). "In this study, we conducted a comprehensive bioinformatics analysis to evaluate the prognostic and therapeutic value of TIMP2 in cancer patients by utilizing a series of databases, including Oncomine, GEPIA, cBioPortal, GeneMANIA, Metascape, and Sangerbox online tool." (PMID 36304987, 2022). "The proven decrease in cognitive functions in patients after cancer treatment, as well as the acceleration of the trajectory of cell aging, may be correlated with a lower level of TIMP-2 in these patients." (PMID 36136069, 2022). "The prognosis of TIMP2 in cancers was performed though the GEPIA database and Cox regression." (PMID 36304987, 2022). "There is also currently some controversy regarding the role that TIMP2 plays in cancers." (PMID 36624735, 2022). "Therefore, in our previous studies, we also compared the serum levels of MMP-2 and TIMP-2 in patients with CRC with their expression in cancer cells, inflammatory infiltrate cells and colorectal cells from adjacent normal tissue." (PMID 34071492, 2021). "Furthermore, cytokine factors were increased, which were associated with immune cell recruitment/activation (MIF-3α), extracellular matrix regulation (TIMP-2), cancer interaction (IL-8, TGF-β2), and angiogenesis regulation (VEGF-A)." (PMID 34443536, 2021). "Clinical ESCC tissues also showed lower expression of TIMP2 than adjacent non-carcinoma tissues." (PMID 34778021, 2021).
cancer (continued). "Moreover, the area under the ROC curve of M-CSF and the combined analysis of M-CSF with CA 125 and SCC-Ag were larger than the area of MMP-2 or TIMP-2 in all stages of cancer." (PMID 30820752, 2020). "Constructed with a substrate sensitive to MT1-MMP, the first MT1-MMP FRET sensor observed epidermal growth factor (EGF)-induced, cytoskeleton-dependent MT1-MMP activity at the leading edge of migrating cancer cells, which can be abolished by tissue inhibitor of metalloproteinase-2 (TIMP-2)." (PMID 33240867, 2020). "TIMP2 may play a key role in facilitating the degradation of the basement membrane and the invasion of surrounding tissues in cancer cells to form metastatic colonies in lymph nodes." (PMID 32595725, 2020). "Macrophage colony-stimulating factor (M-CSF), matrix metalloproteinase-2 (MMP-2) and its specific tissue inhibitor (TIMP-2) may play an important role in the pathogenesis of cancer disease." (PMID 30820752, 2020). "TIMP-2 correlates with poor prognosis in many types of cancer." (PMID 30820752, 2020). "In addition to its MMP-2 dependent functions, TIMP-2 can regulate signalling pathways by direct interaction with the cell surface receptors on normal and cancer cells." (PMID 33023532, 2020). "Since our study demonstrated higher expression of TIMP-2 in high-grade serous ovarian tumours, we used normal secretory Fallopian tube and cancer cell lines that expressed relatively more TIMP-2 than TIMP-1 or TIMP-3, to investigate in vitro the cellular functions of TIMP-2 by transient knockdown." (PMID 33023532, 2020). "Interestingly, MMP-14 has been proposed as an activator of latent MMP-2 in conjunction with tissue inhibitors of metalloproteinase 2 (TIMP-2) for degradation of extracellular matrix and promotion of cancer invasion and metastasis." (PMID 32848608, 2020). "TIMP-2 expression indicates a favorable prognosis in some types of cancer." (PMID 33419373, 2020). "However, in the cancer-induced group, TIMP-2 expression was significantly lower than that in the normal group." (PMID 30787353, 2019). "Our previous investigations performed on GC, CC and EC patients have revealed that the serum concentrations of MMP-2 and TIMP-2 in cancer patients were statistically lower in comparison to healthy subjects and all these differences reached statistically significance." (PMID 30719232, 2019). "Besides, TIMP-2 or MMP-9 expression in cancer tissues was an independent marker for the prognosis of CRC patients by univariate and multivariate Cox regression analysis." (PMID 31293204, 2019). "Our analysis found that the genes which acquire a strong correlation with TIMP2 are associated with the extracellular matrix and cells of a mesenchymal lineage and surprisingly do not differentiate carcinoma subtypes." (PMID 31882975, 2019). "With regards to carcinomas, TIMP2 displays a strong correlation with a large number of genes, many of which belong to components of the matrisome and supporting our idea that TIMP2 function may be modulated at a post-transcriptional level in tumors." (PMID 31882975, 2019). "The results might enrich our knowledge on the tumorigenesis and development of GC, and also present more evidences to clarify the paradoxical role of TIMP2 in cancers." (PMID 29941993, 2018). "Besides, our further Oncomine analysis revealed significant higher TIMP2 in GC than non-cancer tissues, which indicates the potential key role of TIMP2 in the oncogenesis and development of GC (data not shown)." (PMID 29941993, 2018). "For example, the tissue inhibitor of metalloproteinases (TIMP-2) is suppressed in several types of cancers due to hypermethylation of CpG island in the promoter region, thus increasing the invasive capacity of some cancers (prostate cancer, lymphoid malignancies)." (PMID 30103412, 2018).
cancer (continued). "Moreover, Tan IIA inhibited NF-κB signalling and expression of MMP-2 and MMP-9, and increased levels of tissue inhibitor of matrix metalloproteinases type 1 and 2 (TIMP-1 and TIMP-2), therefore suppressed invasion and metastasis of cancer cells." (PMID 30373594, 2018). "In particular, growth-regulated protein (GRO), ENA-78/CXCL5, TIMP-2, and leptin were strongly up-regulated in malignant seroma, whereas IGFBP-1 (insulin-like factor binding protein-1), IL-3, IFN-γ, FGF-9 and IL-16 were down-regulated in malignant versus benign seroma fluid." (PMID 26361584, 2015). "Furthermore this study clarified the role of miRNA-106a in pancreatic tumorigenesis by promoting cancer cell proliferation, epithelial–mesenchymal transition and invasion by targeting tissue inhibitors of metalloproteinase 2 (TIMP-2)." (PMID 26259238, 2015). "Overexpression of TIMP2 protects cancer cells from apoptosis." (PMID 25887408, 2015). "The present meta-analysis evaluated the relationship of TIMP2 -418 G>C polymorphism with the risk of cancer and suggested that the TIMP2 -418 G>C polymorphism did not contribute increased or decreased risk of cancer." (PMID 25136829, 2014). "TIMP-2 is a potent inhibitor of cancer cell invasion through reconstituted ECM." (PMID 24628713, 2014). "It was both in cancer and inflammatory cells that the highest number of positive cases was observed in N1 tumors, although the differences within N subgroup were significant only for the expression of TIMP-2 in inflammatory cells (p = 0.007)." (PMID 24395652, 2014). "Therefore, it is apparent that TIMP-2 plays a broader role both in endothelial cell physiology and in cancer development." (PMID 23371049, 2013). "Furthermore, the NM demonstrated dose-dependent decrease in MMP secretion and increase in TIMP-2 secretion by all these female cancer cells." (PMID 22736175, 2012). "Also, three cancer-associated proteins, GRO, LIF, TIMP-2 were also down-regulated, along with Leptin, an energy intake and expenditure regulator." (PMID 18282300, 2008). "Furthermore, high TIMP-2 expression by cancer cells was present in 225 (41.7%) cases while cancer cells expressed MMP-14 in 4 (0.7%) cases and none expressed MMP-2." (PMID 16776850, 2006). "This may explain contradictory results in which patients with higher TIMP-2 expression either experienced low cancer recurrence/progression or a poor prognosis, emphasizing the overall activating or inhibitory role of TIMP-2." (PMID 16776850, 2006). "Furthermore, it is essential for preventing metastasis by limiting the migration and invasion of cancer cells by upregulating epithelial markers like E-Cadherin and tissue inhibitors of metalloproteinases 2 and 3 (TIMP2 and TIMP3) and downregulating mesenchymal markers like N-Cadherin and ZEB2." (PMID 40563418, 2025). "Therefore, we hypothesize that TIMP2 is a versatile candidate as a novel biomarker and therapeutic target for cancers." (PMID 36304987, 2022). "TIMP‐2 is an interesting candidate for such an analysis, given that TIMPs are involved in numerous biological processes that require tissue remodelling and are thus key players in a range of physiological and pathological processes such as angiogenesis, wound healing, inflammation and cancer." (PMID 33107073, 2021). "Indeed, B7-H3 was implicated in cancer aggressiveness since it was shown to modulate migration, invasion and adhesion to the fibronectin of various cancer cells, including melanoma cells, with the regulation of metastasis-associated proteins MMP-2, TIMP-1, TIMP-2, STAT3 and IL-8." (PMID 34572799, 2021). "In addition, the dual role of TIMP-2 (as the main inhibitor of MMP-2) in cancer is demonstrated." (PMID 32751899, 2020). "However, some diffuse stromal staining of TIMP-2 was also evident in some malignant tumours." (PMID 33023532, 2020). "However, another study reports TIMP2 correlation with cancer progression." (PMID 33333870, 2020).
cancer (continued). "Furthermore, the application of synthetic TIMP2 agonists could possibly lead to a reduction of cancer cell invasion in vivo." (PMID 31836008, 2019). "Thus, the net effect of miR-221/222 on TIMP2 appears to be cancer type specific, and we speculate that this reflects the expression levels of other regulators such as the MYB family proteins." (PMID 30833639, 2019). "Thus, we speculate that a cancer cell downregulates TIMP-2 expression to compensate the insufficiency of hydrolytic collagen induced by AID deficiency." (PMID 30874539, 2019). "However, reported data reveal contradictions regarding the requirement for TIMP-2 in increasing migratory potential, as some report the necessity for TIMP-2 to increase migration of cancer cells overexpressing MT1-MMP, whereas others did not using similar cell models." (PMID 27756325, 2016). "Therefore, it is possible that multiple alleles or genes contribute the susceptibility to cancer risk and TIMP2 -418 G>C analyzed variant do not influence individually." (PMID 25136829, 2014). "Moreover, the intensity of MMP-2 expression in inflammatory cells correlated significantly with the expression of this protein in cancer cells (p = 0.006) and with the expression of TIMP-2 in all types of cells analyzed (p = 0.040, p = 0.003, and p = 0.0495, respectively)." (PMID 24395652, 2014). "Meanwhile, MMP-9 and TIMP-2 could also affect the progression of cancer." (PMID 24829764, 2014). "The present meta-analysis suggests that the TIMP2 -418 G>C polymorphism may not be involved in predisposing risk factor for cancer in overall population." (PMID 25136829, 2014). "However, one observation that we have already noticed is that by increasing the production of TIMP2 to 10 times its original value (i.e., αT = 40) greatly reduces matrix degradation over the time interval considered and the cancer cell population increases by only 56% from its initial value." (PMID 23565505, 2013). "TIMP2 has been identified as a partner of extracellular HSP90, playing a significant role in cancer-related stress responses." (PMID 41369326, 2025). "The interplay between TIMP2 and Aha1 regulates the extracellular MMP2:HSP90 complex, with TIMP2 serving to disrupt MMP2 activity, thus influencing cancer progression." (PMID 41369326, 2025). "As a transcription factor, c-Jun regulated the expressions of N-cadherin, E-cadherin, MMP2, MMP9 and TIMP2, which are involved in EMT and regulate migration and invasion of most cancers." (PMID 40149013, 2025). "This was established by correlating the reduction in TIMP levels with increased cancer cell invasiveness, while supplementation with TIMP-1 (2.1 nM) and TIMP-2 (2.5 nM) significantly inhibited the chemerin-induced migration and invasion responses." (PMID 39590835, 2024). "In lung cancer, which is responsible for the most cancer-related deaths worldwide, quercetin significantly reduced the protein expression of MMP-2 and MMP-9 and increased TIMP-2 expression." (PMID 39335164, 2024). "miR-200b has been shown to target TIMP-2 expression, miR-200c targets FN1 (the fibronectin-coding gene) expression, and both miRNAs act as suppressive miRNAs in cancer cells." (PMID 39001478, 2024). "TIMP-2 traditionally inhibits MMP-2 and -9, but, in aggressive cancers, TIMP-2 uniquely binds and activates pro-MMP-2 and MT1-MMP to stimulate MAPK/ERK signaling." (PMID 38288108, 2023). "Like TIMP2, TIMP4 was found to be up-as well as downregulated in tumors depending on the type of cancer." (PMID 37313172, 2023). "Changes in the expression of TIMP-2 and certain MMPs have been shown to lead to changes in EMT genes in various cancer models." (PMID 36585738, 2022).